MTOR (mechanistic target of rapamycin kinase)
Diseases named in the same sentence as MTOR in open-access papers (continued):
Sharing a sentence is not in itself a finding about the gene and the disease.
colorectal cancer (continued). "A US Food and Drug Administration‐approved drug library containing 616 small molecules is used to screen anticancer drugs against colorectal cancer (CRC) cells that rely on mTOR." (PMID 39513392, 2024). "Conversely, USP22 has been demonstrated to exert an anticancer effect on colorectal cancer by diminishing mTOR activity." (PMID 39143031, 2024). "Based on network analysis, a total of 82 significant pathways were identified which MAPK signaling pathway, FoxO signaling pathway, mTOR signaling pathway, Cell cycle, Focal adhesion, and Colorectal cancer were notable significant pathways." (PMID 38719941, 2024). "It has been shown that Cathepsin G has a tumor-suppressive effect on colorectal cancer cells by controlling the activity of the Akt/mTOR/Bcl2-mediated anti-apoptotic signaling pathway." (PMID 39080685, 2024). "The phosphorylation of AKT catalyzes the activation of the mechanistic target of rapamycin complex 1 (mTORC1), underscoring the significant role of the PI3K/AKT/mTOR signaling pathway in the metabolic reprogramming of colorectal cancer." (PMID 39330497, 2024). "CTSG exerts anti-tumor effects in colorectal cancer by negatively regulating the Akt/mTOR/Bcl-2 signaling pathway, and its overexpression promotes apoptosis." (PMID 39839650, 2024). "The top WikiPathways involved focal adhesion PI3K-Akt-mTOR, PI3K-Akt-mTOR, and focal adhesion pathways, followed by the alpha-6-beta-4 and epithelial to mesenchymal transition in colorectal cancer cascade." (PMID 39456581, 2024). "Constitutive activation of the PI3K/Akt/mTOR signaling are well confirmed in colorectal cancers (CRCs)." (PMID 38169019, 2024). "It has been reported that SNHG7 acts as a ceRNA by sponging miR-34a, which controls the expression of the GALNT7 target gene and promotes the progression of colorectal cancer (CRC) via the PI3K/Akt/mTOR pathway." (PMID 39028420, 2024). "Similar results were seen in colorectal cancer (CRC), where MSC (mesenchymal stem cells) secretions led to activated AMPK/mTOR signaling, causing an increase in migration and proliferation of CRC." (PMID 39201332, 2024). "References 1 Sun L, Jiang C, Xu C, Xue H, Zhou H, Gu L, Liu Y and Xu Q (2017) Down-regulation of long non-coding RNA RP11-708H21.4 is associated with poor prognosis for colorectal cancer and promotes tumorigenesis through regulating AKT/mTOR pathway." (PMID 39569529, 2024). "TQ effectively induces apoptosis, inhibits cell proliferation, and reduces metastasis in colorectal cancer cells by modulating key molecular pathways such as PI3K/AKT/mTOR, NF-κB, STAT3, and MAPK." (PMID 39769996, 2024). "A recent study showed that targeting TIMM44 by a mitochondria-targeting near-infrared (NIR) fluorophore IR-58 activated autophagy and apoptosis in an mTOR-related manner, thereby inhibiting colorectal cancer growth." (PMID 38467612, 2024). "We focused on the effects of LAH on mitochondrial dynamics, mTOR signaling, autophagy, and apoptosis in colorectal cancer (CRC) cells to explore its anticancer potential." (PMID 39404412, 2024). "Depletion of cystine/cysteine by recombinant cyst(e)inase effectively inhibits the growth of colorectal tumors by inducing autophagy in colorectal cancer cells through mTOR-ULK signaling axis." (PMID 39079386, 2024). "For instance, in esophageal cancer cells, Ecn induced apoptosis by inactivating AKT/mTOR signaling pathway, while in colorectal cancer cells, it promoted apoptosis by activating JNK and p38 MAPK signaling pathways." (PMID 37692489, 2024). "These pathways are related to Parkinson’s disease, the mTOR signalling pathway, thyroid cancer, and colorectal cancer, suggesting a potential connection between extensive dairy farm management and enhanced functional properties of the milk produced." (PMID 39457889, 2024).
colorectal cancer (continued). "AC modulates the CXCL8/CXCR2 chemokine axis and inhibits the PI3K/Akt/mTOR pathway in colorectal cancer cells and orthotopic mouse models, thereby exerting anti-metastatic effects on HCC." (PMID 39206194, 2024). "EPHA2 was found to promote the formation of vasculogenic mimicry (VM) in colorectal cancer (CRC) via PI3K/AKT/mTOR and ERK1/2 signaling, and TNF plays a role in angiogenesis by synergistically inducing VEGF production with IL-1beta (IL1B)." (PMID 39596139, 2024). "PDE4B modulates the expression of MYC that leads to low intracellular cAMP levels, activates AKT/mTOR signaling, and promotes cell survival in colorectal cancer." (PMID 36874096, 2023). "The c-Met/PI3K/AKT/mTOR axis can activate the liver metastasis-specific cholesterol metabolism pathway in colorectal cancer, providing conditions for tumor cell colonization and growth in the liver." (PMID 37180578, 2023). "CLDN14, an upregulated prognostic gene, influence colorectal cancer progression through controlling the PI3K/AKT/mTOR pathway." (PMID 37799140, 2023). "In contrast, overexpression of OGT increases phosphorylation and activity of Akt and mTOR, which in turn enhances the proliferation and metastasis ability of colorectal cancer cells." (PMID 37838167, 2023). "Abnormal activation of the mTOR signaling pathway can promote the proliferation, invasion, and metastasis of colorectal cancer cells." (PMID 37511932, 2023). "ABC294640, a SphK2 specific inhibitor, also induced ceramide production and Akt-mTOR inactivation, thereby inhibiting colorectal cancer cell growth in vitro and in vivo." (PMID 37604912, 2023). "In summary, these data indicate that NaB plays important role in development of colorectal cancer via regulating the mTOR activation." (PMID 37185889, 2023). "MUC3A was the top mutated gene in multiple BRCA cell lines and promoted the progression of colorectal cancer through the PI3K/Akt/mTOR pathway." (PMID 37508580, 2023). "The research indicated that FOXO6 knockdown inhibited cell proliferation, migration, invasion and glycolysis of colorectal cancer cells by inhibiting the PI3K/AKT/mTOR signaling pathway." (PMID 37822879, 2023). "several literatures also report that mTOR inhibitors can enhance the anti-colorectal cancer activity of 5-FU." (PMID 37498338, 2023). "An increase in the phosphorylation of AMPK and a decrease in the detection of phosphorylated mTOR have been shown in colorectal cancer cells." (PMID 36334253, 2023). "The PI3K/AKT/mTOR pathway is activated in colorectal cancer when GALNT7 is expressed at high levels, facilitating the disease spread." (PMID 37946148, 2023). "ATL I decreases glucose metabolism in vitro and in vivo by decreasing the Akt/mTOR signaling pathway, and thereby limiting colorectal cancer cell growth." (PMID 37241729, 2023). "Genetic inhibition of OGT in colorectal cancer cells reduces phosphorylation of Akt and mTOR, thus impairing cancer cell proliferation." (PMID 37838167, 2023). "Heat Shock Factor 1 (HSF1) is an oncogene in colorectal cancer, which promotes mTOR activation and glutamine metabolism." (PMID 37127605, 2023). "Previous research found that Menin is closely associated with glycometabolism and Menin inhibitors induced increase in glycolysis occurs in an mTOR-independent manner, which enhances the sensitivity of colorectal cancer cells to EGFR inhibitors." (PMID 36928253, 2023). "Inhibition of the mTOR signaling pathway induces autophagy in colorectal cancer cells, whereas inhibited mTOR signaling attenuates colorectal cancer cell migration and invasion by rapamycin, an mTOR inhibitor." (PMID 37511932, 2023).
colorectal cancer (continued). "Functionally, our result showed the NaB treatment is correlated to the mTOR-dependent ferroptosis and development of colorectal cancer." (PMID 37185889, 2023). "The mTOR pathway is closely related to the proliferation, invasion, and apoptosis of colorectal cancer cells." (PMID 37511932, 2023). "For example, in vitro treatment of colorectal cancer stem cells with Torin‐1, an mTOR inhibitor, decreased cell survival, and tumor inhibiting effects of Torin‐1 suggested its efficacy in CRC treatment." (PMID 36760166, 2023). "We have therefore attenuated mammalian target of rapamycin (mTOR) control of AMPKα1 to generate a mutant colorectal cancer in which AMPKα1 signalling is elevated because AMPKα1 serine 347 cannot be phosphorylated by mTORC1." (PMID 37042113, 2023). "Recently, MELK has been defined as a crucial oncogene that plays indispensable roles in the Akt/mTOR signaling pathway to mediate the progression of colorectal cancer (CRC)." (PMID 37340189, 2023). "As a pilot experiment to demonstrate MOSAICA’s potential for multiomics profiling, we utilized MOSAICA to detect 2 protein targets, Tubulin and Vimentin, and 2 mRNA targets, POLR2A and MTOR in colorectal cancer SW480 cell culture samples." (PMID 35013281, 2022). "The overactivation of the dysregulated PI3K/Akt/mTOR pathway contributes to the progression and proliferation of colorectal cancer cells." (PMID 36139789, 2022). "A previous study from our research team has demonstrated a connection between polycystins and mTOR signalling in colorectal cancer." (PMID 35285136, 2022). "Highlighting that low-expressed HRK prevents apoptosis as well as promotes the proliferation, invasion and migration of colorectal cancer cells through PI3K/AKT/mTOR signaling pathway." (PMID 36568155, 2022). "While full-length SIGIRR negatively regulates mTOR activation, SIGIRRΔE8 interacts with the ATP synthase in the colorectal cancer cells." (PMID 35900274, 2022). "Another study showed that cAMP inhibits MYC activity through the mTOR pathway in a PDE4-dependent manner in colorectal cancer cells." (PMID 35978822, 2022). "Several PI3K, Akt, and mTOR inhibitors have entered preclinical and clinical stages in treating colorectal cancer by achieving cell cycle arrest, cell apoptosis and elimination of cell survival signals." (PMID 36139789, 2022). "mTOR inhibitors are promising in the treatment of infectious diseases, inflammatory bowel disease, and colorectal cancer." (PMID 36293326, 2022). "The downstream transcription factor cyclin D1 is positively regulated by Akt and mTOR, in which the degradation of cyclin D1 would accelerate the G1-phase cell cycle arrest in colorectal cancer cells." (PMID 36139789, 2022). "And for the first time, HRK was shown to promote apoptosis and inhibit proliferation of colorectal cancer cells by inhibiting PI3K/AKT/mTOR signaling pathway." (PMID 36568155, 2022). "The AMPK/mTOR signaling system also has provided numerous prospective therapeutic targets for colorectal cancer." (PMID 36293326, 2022). "More recently, colorectal cancer cells reportedly enter a diapause-like drug-tolerant persister state, concomitant with the reduction of mTOR signaling." (PMID 36396656, 2022). "Based on these results, we found that ASP inhibited cell proliferation, migration and invasion, promoted cell G0/G1 phase block and apoptosis, and inhibited the PI3K/Akt/mTOR pathway to achieve therapeutic effects on colorectal cancer." (PMID 35774597, 2022). "KEGG analysis also showed that KCNJ14 participates in cancer-related signalling pathways in colorectal cancer, such as the mTOR, NOD-like receptor, and VEGF signalling pathways." (PMID 36100894, 2022). "FBXW7 can affect the multiplication and apoptosis of colorectal cancer cells through Notch and Akt/mTOR signaling pathways." (PMID 35965327, 2022). "The PI3K/AKT/mTOR pathway plays a critical role in the occurrence and progression of colorectal cancer." (PMID 35311154, 2022).
colorectal cancer (continued). "This indicates that KCNJ14 regulates the activity of the mTOR signalling pathway in the pathological process of colorectal cancer." (PMID 36100894, 2022). "NLRC3 mediates protection against colorectal cancer by inhibiting the activation of the mTOR signaling pathway." (PMID 35433762, 2022). "An inhibitory effect of DSK on colorectal cancer progression via downregulation of the PI3K-Akt-mTOR pathway has been documented." (PMID 35806120, 2022). "A previous study confirmed that trifolirhizin can induce autophagy via AMPK/MTOR pathway to prevent and treat colorectal cancer." (PMID 36091599, 2022). "In this study, the authors show that RNF43 G659fs is an oncogenic colorectal cancer mutation and sensitizes tumor cells to PI3K/mTOR inhibition." (PMID 35676246, 2022). "FASN positively upregulated the AMPK/mTOR pathway and enhanced proliferation in colorectal cancer cells." (PMID 35742944, 2022). "It has been proved through in vitro and preclinical investigations that mTOR is an effective target for colorectal cancer therapy." (PMID 36293326, 2022). "As confirmation, mTOR expression was shown to be reduced in preclinical models of colorectal cancer (CRC) and melanoma." (PMID 35326491, 2022). "ANXA2 was reported to activate AKT/GSK3β and AKT/mTOR signaling in gastric, breast, and colorectal cancer, whereas ANXA2 is a substrate of ITSN1-L-mediated cell–substrate adhesion through the FAK/integrin β3 pathway." (PMID 35977942, 2022). "Previous study has demonstrated that rolipram was an effective PDE4B inhibitor, which exerted important tumor suppressive effects by inhibiting the PDE4B/mTOR/Myc axis in colorectal cancer." (PMID 34977026, 2021). "Another investigation has proved the crosstalk between JAK2 and mTOR in the regulation of colorectal cancer." (PMID 34316408, 2021). "The concentrations of important molecules (sICAM-1, mTOR, Beclin-1, cathepsin B) involved in the pathogenesis and poor prognosis of colorectal cancer were also evaluated by ELISA." (PMID 33918514, 2021). "The Akt/mTOR signaling pathway, a mechanism potentially related to colorectal cancer growth and metastasis, was shown to be differentially regulated during exercise." (PMID 34638290, 2021). "Inhibition of the PI3K/Akt/mTOR signaling pathway activates autophagy in HT-29 human colorectal cancer cells." (PMID 34439303, 2021). "mTOR has been previously identified as a potential therapeutic target in BRAFV600E-driven colorectal cancer." (PMID 34201061, 2021). "Recently, mTOR pathway has been confirmed to be involved in mediating ferroptosis in different cancers such as colorectal cancer." (PMID 33928101, 2021). "MM131 leads to the inhibition of important proteins engaged in the progression and metastasis of colorectal cancer such as sICAM-1, cathepsin B, and mTOR." (PMID 33918514, 2021). "Therapeutically, inhibition of mTOR signaling with rapamycin have been reported to attenuate the migration and invasion of colorectal cancer." (PMID 33816287, 2021). "Rolipram (Rol) was reported to be an effective PDE4B inhibitor, which exerted important tumor suppressive effects by inhibiting the PDE4B/mTOR/Myc axis in colorectal cancer." (PMID 34977026, 2021). "Recently, a new study has revealed that statins can target inhibition PI3K/AKT/mTOR signaling and thus acts on colorectal cancer progression." (PMID 34603292, 2021). "Mechanistically, increased glutamine metabolism resulting from CDK4/6 inhibition in breast and colorectal cancer cells has been shown to be dependent on MYC-driven activation of mTOR." (PMID 33572972, 2021). "This combination also provided anti-cancer effects toward colorectal cancer by inhibiting mammalian target of rapamycin (mTOR) and Wnt/β catenin signaling pathways and the induction of apoptosis." (PMID 33435215, 2021).